IDO1 (indoleamine 2,3-dioxygenase 1)
Diseases named in the same sentence as IDO1 in open-access papers (continued):
Sharing a sentence is not in itself a finding about the gene and the disease.
infection (continued). "We found that IDO1 was promptly induced in infection at the protein and gene expression levels, maintained elevated thereafter and was associated with increased levels of kynurenines, downstream products of IDO1 with immunoregulatory functions and increased kynurenine to tryptophan ratio." (PMID 23853597, 2013). "In the lungs of the dysbiotic mice, there was an increase in IDO1 (Indoleamine 2,3‐dioxygenase 1) activity and an accumulation of kynurenine after infection, and IDO1−/− mice were resistant to infection after induction of dysbiosis." (PMID 40387573, 2025). "In the present study, however, we have shown that IDO1 plays a previously neglected role in controlling the innate immune response to bacterial infections during infection with P. aeruginosa." (PMID 40387573, 2025). "Infection with influenza A virus and the bacteria Chlamydia muridarium, Chlamydia pneumoniae and Mycobacterium tuberculosis leads to an increase in IDO1 activity and consequently to an accumulation of kynurenine at the site of infection." (PMID 40387573, 2025). "In the context of pathogen infection, IDO1 activity is pleiotropic: it can directly inhibit the replication and spread of certain pathogens, while also acting on host cells to suppress immune responses, thereby promoting viral activities." (PMID 40715093, 2025). "Initially quiescent during mild or subclinical infection, the IDO1-KYN axis becomes hyperactivated as inflammation escalates, leading to Systemic AHR Activation Syndrome (SAAS) and sustained immune dysfunction." (PMID 40949107, 2025). "Overall, these results suggest that AHR expression during infection in dysbiotic mice is secondary to IDO1 activity, and its activation is involved in inefficient control of the bacterial load associated with dysbiosis." (PMID 40387573, 2025). "Previous work has shown an up-regulation of IDO1 expression in human and murine macrophages upon infection with reference M. tuberculosis strains (e.g., H37Rv), and this finding correlated with higher bacterial burden." (PMID 39597535, 2024). "In an inflammatory context sparked by cytokines such as interferon-γ, tumor necrosis factor α, and pathogenic infections such as influenza A virus or SARS-CoV2 infection, the activation of IDO-1 leads to the production of Kyn." (PMID 38534967, 2024). "Another intriguing finding is the heightened expression of Indoleamine 2,3-dioxygenase 1 (Ido1) in response to infection in overfed-infected animals compared to normal-fed animals." (PMID 39469711, 2024). "Ccr7+Ido1+ DCs, Cd160+Cd8+ T cells, and Tnfrsf4+Cd4+ T cells all increased after infection, and were viral RNA-positive, suggesting direct involvement of these immunity hubs against SARS-CoV-2 infection." (PMID 39414763, 2024). "The expression of IDO1 and IL-1β in the infected cells was stronger with all virulent M. tuberculosis strains, compared to infections with the avirulent strain." (PMID 39597535, 2024). "Specifically, our group showed that 5-HT promoted pathogen clearance and immune homeostasis in infection by balancing between the host IDO1/kynurenine pathway and the microbial indole/AhR pathway." (PMID 38721278, 2024). "Coronaviruses (CoV) can activate AhR and establish infection through the IDO1-kynurenine-AhR signaling pathway." (PMID 38978778, 2024). "TLR2KO mice showed a reduced frequency of lung-infiltrating PMN-MDSCs expressing IDO-1 at two- and eight-weeks post infection, along with a reduced number of these cells after 2 weeks of infection, compared to wild-type controls." (PMID 37524886, 2023). "qPCR analysis confirmed that Ido1 mRNA expression was strongly induced during daytime infection, with a peak at 7 dpi." (PMID 36896128, 2023). "This differential response, as observed in a variety of studies using many different models of infections, is driven by the circadian clock controlling many aspects of the immune response, and we propose that the regulation of IDO1 expression is one of them." (PMID 36896128, 2023).
infection (continued). "Consistent with reduced IFNγ expression, the mRNA induction of Nos2, Gbp1, Gbp2, Gbp4, Gbp5, Ido1 and Acod1 was severely impaired in the spleens of Myd88−/− mice after intraperitoneal infection." (PMID 36479617, 2023). "IDO1 is expressed in a variety of immune cells, including dendritic cells and monocyte-derived cells, and is induced during infection by several pro-inflammatory cytokines through IFN-γ-dependent or independent mechanisms." (PMID 36896128, 2023). "Reduced numbers and frequencies of IDO-1+ M-MDSCs were observed in the lungs of Dectin-1KO mice at weeks two and eight post infection compared to WT controls." (PMID 37524886, 2023). "By resorting to a clinically relevant murine model of CF, we observed that, despite its reduced activity, Ido1 maintains its circadian rhythmicity, thus driving a day–night response to infections in CF." (PMID 36896128, 2023). "This suggests that the Tph1/5-HT, by sustaining the IDO1 and restraining AhR activation, exerts a critical control upon the dynamic activation of the two pathways in infection." (PMID 37717018, 2023). "We intranasally infected mice at ZT3 and ZT12, time of low and high expression of Ido1, and collected tissues at 1, 3, and 7 days post-infection (sacrifice of mice infected at ZT3 was performed at ZT3; sacrifice of mice infected at ZT12 was performed at ZT12)." (PMID 36896128, 2023). "Activation of IDO1 expression in the TME or in intracellular pathogen infection leads to a depletion of TRP and the corresponding production of KYN." (PMID 35245456, 2022). "Accordingly, our data demonstrated that, in the spleen, IDO1 was highly upregulated in mice upon infection with E. multilocularis." (PMID 36439161, 2022). "Taken together, these results suggest that IDO1 signaling suppresses DCs maturation during infection with E. multilocularis." (PMID 36439161, 2022). "In contrast, splenic CD11c+MHC II+ DCs in E. multilocularis infected mice exhibited significantly higher frequency and intensity of IDO1 1-, 2- and 3- month post infection." (PMID 36439161, 2022). "Ido-1 is a natural immune-regulatory enzyme initially thought to be solely implicated in the modulation of innate immune responses during infection, subsequent discoveries demonstrated Ido-1 as a mechanism of acquired immune tolerance." (PMID 36419183, 2022). "IDO1-/- mice exhibited a significantly lower parasite load compared to WT mice 2- and 3- month post infection (p<0.05 or p<0.01)." (PMID 36439161, 2022). "IDO1 mRNA levels in infected mice continued to increase for 3 weeks after infection, whereas IDO2 mRNA levels showed an opposite trend." (PMID 35045867, 2022). "Our results indicate that engagement of the IDO1 signaling promotes metacestode progression during infection with E. multilocularis." (PMID 36439161, 2022). "Taking these findings together, it is suggested that IDO1 inhibits the HIV-1 vector infection through autophagy facilitated by tryptophan depletion." (PMID 35883685, 2022). "The data demonstrated higher Kynurenine levels and higher IDO-1 activity during the acute phase of infection compared to the chronic phase." (PMID 35456119, 2022). "MRI examination was used to depict the liver metacestode tissues of infected WT and IDO1-/- mice, among which WT mice showed more extensive parasite lesions than IDO1-/- mice in month 2 and 3 after infection." (PMID 36439161, 2022). "Based on the obtained results, it was established that IDO1 increased mortality rates through a decrease in recruited neutrophils and mononuclear cells into the infection focus via a reduction in chemokine production." (PMID 36010680, 2022). "Among the infection-induced genes, ido1 and tdo2 were found, but for robust protein-level induction of IDO1, the addition of IFNG was needed." (PMID 34819931, 2021).
infection (continued). "In the acute infection stage, the expression of IDO1 is upregulated to promote the process of anti-viral defense, as IFN-γ did so in HCV-infected liver cells to inhibit anti-HCV T cells in the chronic infection phase." (PMID 34869457, 2021). "The authors identified a modest increase in IDO1 expression in the cerebellum and hippocampus of neonatal rats during infection, while immune competent adult rats show a marked increase of IDO1 expression in the cerebellum and hemispheres of the brain." (PMID 34095234, 2021). "For example, primary nasal epithelial cells treated with the IDO‐1 inhibitor 1‐D‐methyl tryptophan (1‐MT) showed reduced production of pro‐inflammatory cytokines including IL‐7 and G‐CSF upon infection with the PR8 strain of influenza A virus." (PMID 33124149, 2021). "A recent study found that aged AM from 18–20-month-old BALB/c mice exhibit decreased indoleamine-pyrrole 2,3-dioxygenase (IDO1)-dependent tryptophan metabolism following PR8 infection." (PMID 34152253, 2021). "Although initially thought to be solely implicated in the modulation of innate immune responses during infection, subsequent discoveries demonstrated IDO1 as a mechanism of acquired immune tolerance." (PMID 33072086, 2020). "Lung leukocytes were obtained 96 h, 2 and 10 weeks after infection, and the number of IDO-1+ and AhR+ cells was determined by flow cytometry." (PMID 32647342, 2020). "Although chlamydial death due to tryptophan depletion via IFN-γ-induced IDO1 axis, has been well characterized in vitro, relatively few studies have measured IDO1 expression levels and its enzymatic activity in the actual infection site." (PMID 30832593, 2019). "This antiparasitic effect was due to IDO1-mediated tryptophan degradation, since the supplementation of l-tryptophan at the timepoint of infection abrogated the effect." (PMID 31267172, 2019). "Surprisingly, we also observed a significant upregulation in IDO1 expression levels in women who cleared their infection post antibiotic treatment (PAT)." (PMID 30832593, 2019). "To assess the impact of IDO activity on C. muridarum growth we inhibited IDO1-2 by 1-MT treatment starting from seven days before infection to seven days post infection." (PMID 31249813, 2019). "Despite the small number of patients we found that C. trachomatis infected women, either single or repeated infection, had significantly higher IDO1 expression levels." (PMID 30832593, 2019). "The potential tryptophan degradation to kynurenine pathway during C. trachomatis infections in women with single or repeated infection was evaluated by the expression levels of IDO1 in swab samples." (PMID 30832593, 2019). "Here, we sought to measure IDO1 expression levels and related immune markers during different C. trachomatis infection statuses (repeated vs single infection vs post antibiotic treatment), in vitro and in vivo." (PMID 30832593, 2019). "Although, we found that Ser mutant of β-catenin as well as Tyr mutant of IDO1 provided protection against infection." (PMID 30770800, 2019). "Various in vitro studies with C. trachomatis-infected cell lines have also shown the important role of IFN-γ in eliminating infection, due to the induction of the enzyme indoleamine 2,3-dioxygenase 1 (IDO1)." (PMID 30832593, 2019). "This stable tyrosine-mutant IDO1 provided protection against infection through kynurenine catabolism." (PMID 30770800, 2019). "Whereas, women who cleared their infection post antibiotic treatment, had increased levels of IDO1 and TGF-β1, as well as FoxP3." (PMID 30832593, 2019). "As kinase is the signature molecule for phosphorylation of different cellular proteins, thus, chances of phosphorylation of over-expressed IDO1 were reduced, and un-phosphorylated IDO1 remained stable to prevent infection." (PMID 30770800, 2019). "We show that an hCMV infection of hRPE cells blocks IDO1 and iNOS mediated antimicrobial defense mechanisms necessary for the control of S. aureus and T. gondii." (PMID 30781494, 2019).
infection (continued). "The differential expression of IDO1 in bystander and infected cells after IFNγ exposure was recapitulated using infections at increasing IFU/mL, which resulted in the infections of 2%, 26% and >95% in A2EN cells." (PMID 29855501, 2018). "Timing appears to be critical as the authors found that pre-treatment of cells with IFN-γ prevents progression of C. trachomatis along the normal developmental cycle, whereas an existing infection will block IDO-1 expression." (PMID 30619780, 2018). "Further, we found increased expression of M1 macrophage markers Ccl8, Ido1, and Tnfsf13b in Stat2−/− mice during super-infection when compared to WT mice." (PMID 30337919, 2018). "Whereas, the rates of T. gondii-infected wild-type or IDO1-KO cells were comparable 3 and 24 h post infection, indicating that IDO1 inhibits T. gondii replication in IFN-γ-stimulated HAP1 cells." (PMID 30283439, 2018). "Infection with influenza virus has also been shown to increase the expression level of IDO1 in vitro and in vivo." (PMID 28273165, 2017). "In our MCMV-associated sHLH mouse model, mice were sacrificed at day 5 post-infection, and IDO1-KO mice had similar viral titers as compared to WT mice." (PMID 26914138, 2016). "The induction of Ido1 and Ido2 transcripts by IFNγ within OHSCs mimics the cytokine-mediated response of the brain to a peripheral infection." (PMID 27142940, 2016). "Initially recognized in infection because of antimicrobial activity (“tryptophan starvation” of intracellular parasites), IDO1 is now widely recognized as suppressor of acute inflammatory responses and regulator of mammalian immune homeostasis." (PMID 25360137, 2014). "It has been known for decades that IDO1 is induced during infections and displays antimicrobial activity." (PMID 24904580, 2014). "Prior infection with X31 virus protected B6 and IDO1-KO mice from lethal PR8 infection and as expected, sterile viral (PR8) clearance occurred faster (5 dpi) in both mouse strains (data not shown)." (PMID 23785507, 2013). "As expected, lung Kyn levels were below detection limits during primary infection and after viral clearance in X31-infected IDO1-KO mice." (PMID 23785507, 2013). "Mice lacking intact IDO1 genes (IDO1-KO mice) exhibited significantly lower morbidity after sub-lethal PR8 infection, and genetic or pharmacologic IDO ablation led to much faster recovery after virus clearance." (PMID 23785507, 2013). "Bacterial burden in WT and IDO-1−/− mice in lungs, spleen, and livers were similar during the course of infection." (PMID 22649518, 2012). "When THP-1 macrophages were infected with OT, transcription of IDO1 was directly induced by OT infection early after infection." (PMID 22860140, 2012). "Secondly, the use of L-Kyn to L-Trp ratio as an indicator of IDO1 activity in THP-1 cells was unfortunately limited by the drop of L-Trp below the detectable level since the first day post infection." (PMID 22860140, 2012). "Human monocyte-derived DCs and macrophages strongly upregulated the expression of IDO1 after infection with M. tuberculosis; live bacteria induced stronger expression compared to heat-killed or irradiated bacteria." (PMID 22844400, 2012). "Despite its protective role in a variety of infections, IDO1 activation paradoxically appears to be involved in suppression of the immune responses." (PMID 22860140, 2012). "Similarly, we have shown that infection with P. aeruginosa leads to an accumulation of kynurenine in the lung, demonstrating for the first time the increase in IDO1 enzyme activity during P. aeruginosa infection." (PMID 40387573, 2025). "Interestingly, the expression levels of CitH3, NE, MPO, PR3, and PAD4 in IDO1-KO mice after infection were lower than those in WT mice; the same was true for the levels of free DNA and MPO–DNA complexes." (PMID 40597301, 2025).
infection (continued). "Moreover,we found increased SLC7A5 and IDO1 expression in rhesus andhuman blood, suggesting that peripheral leukocytes catabolize tryptophaninto kynurenine during infection." (PMID 41180073, 2025). "In addition, the antigens of E. granulosus can induce immune tolerance and facilitate infection by upregulating the expression of IDO1." (PMID 40597301, 2025). "Our findings provide a new insight in understanding the mechanism of how hvKp manipulate the host immune systems and suggest that pharmacological inhibition of IDO1 could be an effective therapeutic strategy for combating hvKp infection." (PMID 40096073, 2025). "Whereas some DEGs were up-regulated to comparable levels in all infections (e.g., TNFAIP6), some DEGs, such as IDO1 and IL-1β, were up-regulated to comparable levels in all infections with the virulent reference strains but expressed less in cells infected with the avirulent strain H37Ra." (PMID 39597535, 2024). "We have already shown that IDO1 inhibition greatly exacerbated mucosal C. albicans infection and associated inflammatory pathology as a result of deregulated innate and adaptive/regulatory immune responses, an effect in line with the induced IDO1 activity at sites of infection." (PMID 38721278, 2024). "It is well described that the innate immune response depletes cellular tryptophan in response to infection via the host enzyme indoleamine 2,3-dioxygenase (IDO-1) that converts tryptophan to N-formylkynurenine, which is a potent negative regulator of inflammation." (PMID 39186777, 2024). "Although the exact mechanisms behind this phenomenon have not been fully elucidated, one possible explanation is that inhibition of IDO1 accelerates the migration of T cells to the lungs early in infection, thereby strengthening the host’s immune control over Mtb." (PMID 39438693, 2024). "Interestingly, we found that after infection with Mtb, the expression level of only IDO1 significantly increased in inflammatory macrophages, whereas other tryptophan-degrading enzymes, such as IDO2 and TDO2, did not significantly change." (PMID 39438693, 2024). "Moreover, the infection induced the increase of the IDO1 gene expression in the distal small intestine of lambs from the peak of infection." (PMID 38756777, 2024). "A degree of co-expression of genes with proposed opposing effects on M.tb, e.g., IL1B and IFNG (better control) versus IDO1 and Type 1 IFNs (reduced control) – suggests counteracting influence on growth during the early phase of infection and requires further experimentation." (PMID 37333188, 2023). "Additionally, we detected a reduced frequency of PMN-MDSCs expressing IDO-1 in TLR4KO mice at eight weeks post infection." (PMID 37524886, 2023). "Data on gene-fold change for IFNB1, CCL5, CXCL11, CXCL10, and IDO1 after experimental infection of HLMVEC by pathogenic (ANDV, HTNV) and nonpathogenic (PHV) viruses were recorded at seven timepoints t = 0, 12, 24, 36, 48, 60, 72 hpi." (PMID 37766212, 2023). "IDO1 in particular, has been the subject of intense research for its role in maintaining homeostasis and plasticity of the immune system, and its involvement in diseases ranging from allergy to infection and cancer." (PMID 36896128, 2023). "We found that 5-HT produced by mast cells essentially contributed to pathogen clearance and immune homeostasis in infection by promoting the host protective indoleamine-2,3-dioxygenase 1/kynurenine pathway and limiting the microbial activation of the indole/aryl hydrocarbon receptor pathway." (PMID 37717018, 2023). "To better elucidate how IDO1 circadian regulation influences the host response to Aspergillus infection, we analyzed the transcriptional induction of the Trp metabolic pathway during infection." (PMID 36896128, 2023).